RUNX2 (RUNX family transcription factor 2)
Diseases named in the same sentence as RUNX2 in open-access papers (continued):
Sharing a sentence is not in itself a finding about the gene and the disease.
breast carcinoma (continued). "This demonstrated that NGR1 induced ferroptosis in breast cancer cells by regulating RUNX2." (PMID 38885076, 2024). "Furthermore, deletion of Runx2 has been shown to impair mammary stem regeneration, with a potential parallel to mammary tumors and their regenerative potential." (PMID 38059614, 2024). "Therefore, breast cancer cells expressing RUNX2 and CBFβ can exploit the various growth factors involved in the homeostasis of bone formation to allow tumor cell mediated osteoclastogenesis and growth of metastatic cells in this environment." (PMID 36831308, 2023). "Additionally, we have examined the expression of miR-218, Runx2, and Rictor in breast cancer in The Cancer Genome Atlas (TCGA) samples in UALCAN database." (PMID 37968694, 2023). "Bone-derived breast cancer with Runx2 expression shows elevated autophagy." (PMID 36831154, 2023). "Similarly, we showed that ABL-mediated RUNX2 phosphorylation is also required for breast cancer invasion through an increase of MMP13 transcripts that is independent of TAZ-mediated RUNX2 activation." (PMID 36911671, 2023). "RUNX2 promotes the attraction and adhesion of breast cancer cells to the bone and confers cancer cell survival and bone colonization advantages in mice through its transcriptional target integrin α5, establishing integrin α5 as a potential target for preventing bone colonization." (PMID 37296983, 2023). "Runx2 is a transcription factor crucially controlling bone development and also a facilitator of autophagy in different disease paradigms, such as osteogenesis, breast cancer, and vascular calcification." (PMID 36302650, 2023). "An alternative small molecule inhibitor (CADD522) has been shown to block RUNX2 gene regulation by interfering with RUNX2-DNA binding and could antagonize the growth of breast cancer cells." (PMID 36831308, 2023). "Another breast cancer study indicated that RUNX2 could induce the invasion and further drive the adhesion and attraction of cancer cells to bone via the inhibition of SOD2 and PPARα expression." (PMID 37108164, 2023). "Furthermore, miR-218 delivery via ADMSC-exosomes led to a significant decrease in Runx2 and Rictor mRNAs levels in breast cancer cells." (PMID 37968694, 2023). "Hypoxia induced Runx family transcription factor 2 (RUNX2) transcriptionally activates the lncRNA RBM5-AS1 which is involved in maintaining breast cancer stemness through stabilizing the β-catenin-TCF4 transcriptional complex by preventing β-catenin degradation." (PMID 37583933, 2023). "Furthermore, in a comprehensive TMA of human breast cancers, high expression of RUNX2 was correlated with ER-negative disease and poor prognosis of patients as well as inducing preneoplastic changes in naïve murine mammary epithelial tissue." (PMID 36831308, 2023). "Breast cancer stem cells characterized as CD44+/CD24−/low were regulated by RUNX2." (PMID 37108164, 2023). "MMP13 has been reported as a downstream marker of RUNX2 in breast cancer cells." (PMID 37256183, 2023). "RUNX2 has been identified as an oncogene, which could activate the PI3K/AKT pathways to promote the development of breast cancer, and RUNX2 has been identified as a biomarker for osteosarcoma development." (PMID 35340229, 2022). "Notably, current literature has suggested the critical role of RUNX2 for malignant progression of breast cancer by modulating the CD44 +/CD24- breast cancer stem cells." (PMID 36483054, 2022). "We found that the expression of RUNX2 was concurrently upregulated in breast cancer samples." (PMID 35534547, 2022). "miR-30 family members reduced the expression of Runx2 in MDA-MB-231 breast cancer cells." (PMID 35158995, 2022).
breast carcinoma (continued). "Several studies have demonstrated that BMP-2 could also upregulate some bone metabolic factor, e.g., RANKL and RUNX2, to induce breast cancer cells acquire osteoblastic characteristics." (PMID 34983451, 2022). "Similarly, increased expression of Runx2, another key bone metastasis marker in breast cancer, has been associated with increased TGF-β signaling and enhanced bone colonization of breast cancer cells." (PMID 35903297, 2022). "It has been reported that RUNX2 is upregulated in various cancer types and may drive breast cancer cell growth and metastasis." (PMID 35851595, 2022). "Together, these data revealed that RUNX2 might be involved in breast cancer progression and bone metastasis." (PMID 35534547, 2022). "Of note, Vishal and the colleagues further reviewed the potential dysfunction and regulation of RUNX2 in breast cancer mediated bone metastasis, yet the regulatory mechanism during the metastatic process and drug resistance in triple negative breast cancer was insufficiently disclosed." (PMID 36483054, 2022). "Meanwhile, in Vishal’s study, RUNX2 was found to promote breast cancer metastasis to bone." (PMID 36429115, 2022). "We found that RUNX2 knockdown increased epithelial markers and decreased mesenchymal marker expression, which was partially rescued via the co-knockdown of PPARα, indicating that RUNX2 could promote breast cancer cells invasion by repressing PPARα expression." (PMID 35534547, 2022). "More recently, Li and colleagues have also demonstrated the involvement of hypoxia-induced long non-coding RNA RBM5-AS1 in mediating proliferation, migration, invasion, EMT, and stemness maintenance in breast cancer cells under the control of RUNX family transcription factor 2 (RUNX2)." (PMID 35663403, 2022). "The Runx2-dependent microtubule acetylation and its impact on autophagy may help elucidate new mechanisms of breast cancer bone metastatic cell function." (PMID 35884497, 2022). "The expression of RUNX2 was highest in breast cancer patients with bone metastasis." (PMID 35534547, 2022). "Notably, we showed that overexpression of RUNX2 not only promoted EMT but also stemness of breast cancer cells." (PMID 35534547, 2022). "Breast cancer cells with high runt-related transcription factor 2 (RUNX2) expression could secrete EVs with high levels of cadherin 11 (CDH11) and integrin α5 (ITGA5), which synergistically promote osteogenic PMN formation." (PMID 36430471, 2022). "The inhibition of DLX6-AS1 attenuated the breast cancer cell invasion by repressing RUNX2." (PMID 36613528, 2022). "Taken together, the data presented above indicated that in breast cancer, hypoxia-induced RUNX2 could facilitate RBM5-AS1 transcription." (PMID 35110544, 2022). "In addition, CaSki cells are derived from the metastatic site, and the results of RUNX2 expression agree with those reported in the metastatic cell lines MDA-MB-231, Sum49 and Sum59 of breast cancer, which have high expression of RUNX2." (PMID 35805994, 2022). "Similarly, experiments with RUNX2 depletion indicated that the inhibition of bone metastasis in breast cancer cells by knockdown of PPARα was dependent on RUNX2, at least partially." (PMID 35534547, 2022). "Strikingly, RUNX2 expression is upregulated in multiple human carcinomas, including breast cancer." (PMID 35534547, 2022). "In breast cancer, RUNX2 and FOXM1 induce EMT and are regulated by sumoylation, and they share DNA binding sites in ERα; this association leads to the activation of genes involved in proliferation and metastasis and the development of endocrine resistance during tamoxifen treatment." (PMID 36551878, 2022). "Meanwhile, high expression of Runx2 plays a role in breast cancer metastasis." (PMID 35342401, 2022). "In breast cancer, the expression of RUNX2 was higher than that of RUNX1 and RUNX3." (PMID 35534547, 2022).
breast carcinoma (continued). "Taken together, these studies suggest that crosstalk between cell signaling pathways and Runx2 could lead to invasive cellular behavior that may contribute to the bone metastasis of breast cancer." (PMID 34503118, 2021). "In human primary breast cancer cells from two sources, A5 CM reduced the Runx2 and MMP9 levels." (PMID 34230453, 2021). "Indeed, in prostate carcinoma cells, Runx2 is expressed and correlates with metastatic potential, while in breast carcinoma cells Runx2 increases with respect to normal mammary tissue and regulates the expression of osteoblast-related genes." (PMID 34572548, 2021). "Moreover, activation of RUNX2 by AKT has more impact and was better investigated in prostate cancer than in breast cancer since prostate cancer mainly causes osteoblastic lesions, and RUNX2 depicts a pro-osteogenic transcription factor." (PMID 34064589, 2021). "Moreover, a recent study confirms the association between unfavorable prognosis in breast cancer with upregulated SET7/9 expression, describing a carcinogenicity mechanism of SET7/9 through activation of Runt-related transcription factor 2 (RUNX2)." (PMID 34552922, 2021). "RUNX2 has been shown to have an antagonistic role in estradiol-induced breast cancer proliferation." (PMID 34485309, 2021). "Notably, the downregulation of Snail, Runx2, and TGFβ by dopamine was observed in three sources of primary human-breast-cancer cells." (PMID 34031366, 2021). "Interestingly, sclerostin was shown to be a transcriptional target of Runx2 and secreted by both breast cancer and myeloma cells." (PMID 34503118, 2021). "Indeed, previous studies have also found that the silencing of NUPR1 down-regulates runt-related transcription factor 2 (RUNX2), a protein that is highly sensitive to iron overload, and ultimately causes premature senescence in breast cancer cells." (PMID 34359572, 2021). "In contrast, RUNX2 has also been demonstrated to promote tumorigenesis in breast cancer." (PMID 34485309, 2021). "RUNX2 deletion prolongs overall survival (OS) in mice with breast cancer." (PMID 34485309, 2021). "More specifically, in breast cancer, Runx2 has been demonstrated to promote bone metastasis." (PMID 31487369, 2020). "Inspired by the potential involvement of several transcription factors such as Runx-2 and Bach1 in breast cancer bone metastasis, we searched for an additional transcription factor(s), which is associated with augmented proliferation of 4T1.3 clone in a bone cavity." (PMID 33081224, 2020). "Therefore, Runx2 is critical for the CXCL1-induced osteomimetic phenotype by activating the transcription of BRGs in breast cancer cells." (PMID 33123472, 2020). "In particular, the over-expression of RUNX2 promotes prostate and breast cancer metastasis." (PMID 33287223, 2020). "Abnormally elevated SET7/9 expression could enhance breast cancer proliferation migration and invasion via activation of RUNX2 from transcription level." (PMID 32102992, 2020). "They suggested that miR-205 could inhibit breast cancer malignancy by regulating RUNX2, and miR-205 is a tumour suppressor during breast cancer development." (PMID 32961774, 2020). "Downstream, ANCR could inhibit breast cancer cell migration and breast cancer metastasis by decreasing RUNX2 in vitro and in vivo." (PMID 33123287, 2020). "In addition, RUNX2 induces PI3K/Akt activation in breast cancer cells; RUNX2’s contribution to breast cancer invasiveness via mTORC2 has also been shown." (PMID 32168858, 2020). "Finally, recent studies have attested that RUNX2 plays a key role in the interaction between breast cancer cells and the bone microenvironment." (PMID 32650752, 2020). "Additionally, RUNX2 was found to be overexpressed in chemoresistant osteosarcomas, non-small cell lung cancers (NSCLCs), and breast cancers, thereby raising the legitimate question of its role as a tumor-driving transcription factor." (PMID 32230926, 2020).
breast carcinoma (continued). "The interpretation of TRIM21/SET7/9/RUNX2 axis leads to a deeper comprehend about the molecular properties of breast cancer malignancy, and might be an attractive target for its diagnosis and therapy." (PMID 32102992, 2020). "Moreover, high RUNX2 expression has already shown to be predictive of breast cancer recurrence and it has been reported for thyrocytes to have an increased expression of RUNX2 in PTC tissues." (PMID 33374380, 2020). "Alcohol enhances Runx2 expression in ER+ breast cancer cell line, MCF-7." (PMID 31781337, 2019). "In addition, very recent studies indicate that Runx2 is overexpressed in human biopsies of breast cancer (unpublished)." (PMID 31781337, 2019). "Alcohol enhances Runx2 expression in ER+ breast cancer cells." (PMID 31781337, 2019). "LncRNA-NORAD activated TGF-β/RUNX2 signaling pathway in breast cancer cells." (PMID 30930692, 2019). "The results indicate that Runx2 is overexpressed in human biopsies of breast cancer (unpublished)." (PMID 31781337, 2019). "Furthermore, the knockdown of RUNX2 reduced the expression of FGFR2 in the breast cancer cell line MCT-758." (PMID 30202094, 2018). "ZEB1 binding to RUNX2 and Smad motifs in breast cancer cells appears functionally likely, as RUNX2 regulates mesenchymal progenitor to osteoblast differentiation, and mutations in RUNX2 perturb the RUNX2‐Smad association, linking to syndromes of craniofacial dysplasia." (PMID 29744893, 2018). "Similarly, RUNX2 was aberrantly overexpressed in breast cancer cells and promoted their progression." (PMID 29558908, 2018). "In breast cancer, miR-10a-5p promotes cell migration, which is positively regulated by RUNX2." (PMID 29615098, 2018). "As expected, targeting of RUNX2 suppressed breast cancer progression and bone metastasis." (PMID 29558908, 2018). "Indeed, pharmacological delivery of synthetic miR-135 and miR-203 mimics into metastatic breast cancer cells reduces Runx2 protein abundance and consequently, diminishes tumor growth and spontaneous metastasis to bone." (PMID 29780354, 2018). "Besides being necessary for osteogenic differentiation, RUNX2 also plays a role in several tumor tissues, including pancreatic cancer, breast cancer, ovarian epithelial cancer, prostate cancer, lung cancer, and osteosarcoma." (PMID 30463392, 2018). "In addition, deletion of RUNX2 in human breast cancer cells resulted in reduced tumorigenic properties, such as invasion and migration." (PMID 28412963, 2017). "Finally, we detected the expression of ANCR and RUNX2 in breast cancer cell lines (MCF7, T47D, MDA-MB-231, MDA-MB-231HM and BT549), compared with human normal mammary epithelial cell MCF10A." (PMID 28978036, 2017). "Both RUNX1 and RUNX3 have tumor suppressor roles in breast cancers, while RUNX2 is tumor-promoting." (PMID 28412963, 2017). "Runx2 gene deletion resulted in disrupted alveolar progenitor cell populations, differentiated cell type histology, reduced levels of cell proliferation, reduced tumor burden, and longer overall survival in a mouse model of breast cancer." (PMID 28412963, 2017). "The results revealed that ANCR expression may be negatively correlated with RUNX2 expression in breast cancer cell lines." (PMID 28978036, 2017). "Indeed, aberrant Runx2 expression in metastatic breast cancers altered the activity of PI3K, mTORC1, and AMPK, which function as upstream modulators of autophagy." (PMID 29145850, 2017). "In addition, we uncovered a negatively correlated expression pattern between ANCR and RUNX2 in breast cancer tissues and several breast cancer cell lines." (PMID 28978036, 2017). "As might be anticipated, then, Runx2 knock down in a breast cancer cell line reduced metastatic dissemination, suggesting a link between Runx2 and autophagy." (PMID 29145850, 2017).
breast carcinoma (continued). "The CADD522compound also delayed and/or inhibited tumor formation in an aggressive spontaneous model of mammary carcinoma and reduced tumor growth of a RUNX2-expressing patient-derived xenograft (PDX), supporting that CADD522 has therapeutic potential for BC in vitro and in vivo." (PMID 29050333, 2017). "Furthermore, we demonstrated that RUNX2 serves as a master mediator of the formation of an osteomimetic phenotype by activating the transcription of BRGs in breast cancer cells." (PMID 27806311, 2016). "RUNX2 was shown to upregulate miR-10a/b and promote breast cancer cell migration and invasion." (PMID 26404249, 2015). "Subsequent analyses support their functional relevance to breast cancer risk that FGFR2 polymorphisms located in intron-2 alter the binding of two transcription factors, Oct-1/Runx2 and C/EBPb, resulting in an increase of FGFR2 gene expression both in cell lines and in breast tissue." (PMID 26421298, 2015). "RUNX2 appears especially important in estrogen-negative breast cancer, and its level is directly associated with a poor prognosis in this type of breast cancer." (PMID 26404249, 2015). "In breast cancer MCF-10A cell line, elevated RUNX2 was associated with upregulation of D1." (PMID 26404249, 2015). "Similarly, RUNX2 is highly expressed in a small percentage of human breast cancers and its expression correlates with triple negative tumours." (PMID 26489514, 2015). "Thus RUNX2 expression is associated with WNT driven mouse models of breast cancer, confirming the link between activated WNT pathway and RUNX2 expression in normal and transformed mammary epithelium." (PMID 26489514, 2015). "In summary, it may be concluded that, not only the expression of estrogen receptors, but also the expression of RUNX2, can differentiate types of breast cancer." (PMID 26404249, 2015). "Furthermore, RUNX2 appears to be associated with WNT signalling in the mammary epithelium and is specifically upregulated in mouse models of WNT-driven breast cancer." (PMID 26489514, 2015). "The exact mechanism of interaction between RUNX2 and cyclin D1 in breast cancer is not fully known, although it may have features of those in osteoblasts lineage." (PMID 26404249, 2015). "In fact, another study confirmed that ER was capable of inhibiting RUNX2 in breast cancer cells." (PMID 26404249, 2015). "Estradiol and RUNX2 were reported to have an opposite effect on breast cancer metastatic cells." (PMID 26404249, 2015). "Another study showed that RUNX2 could be a key component responsible for breast cancer metastasis to bone." (PMID 26404249, 2015). "However, the inter-relationship between RUNX2 and miR-10a/b and their joint impact on prognosis in breast cancer has yet to be investigated." (PMID 25266482, 2014). "Importantly, our clinical-laboratory correlative analyses indicate that breast cancer patients with higher expression of RUNX2 and miR-10a/b – either individually or jointly – tend to suffer a greater risk of recurrence or death." (PMID 25266482, 2014). "In contrast, RUNX2 mainly exhibits oncogenicroles in breast cancer by promoting invasiveness and metastasis via its target,SNAI2; however it may also play a tumor suppressor role in breast cancer byantagonizing ERα (thus, similar to RUNX3)." (PMID 25415051, 2014). "Importantly, RUNX2-expressing tumours were expressed at a significantly higher rate in ER-negative (13/131; 10%) compared with ER-positive (9/281; 3%) breast cancers (P=0.005; chi-square test)." (PMID 24626992, 2014). "Thus, suppression of RUNX2 reduced miR-10a/b expression, and thereby impairing breast cancer cell motility." (PMID 25266482, 2014). "Thus, overexpression of RUNX2 upregulated miR-10a/b expression, thereby promoting breast cancer cell motility." (PMID 25266482, 2014). "RUNX2 regulates the expression of extracellular matrix proteins and cross-talk between epithelium and stroma is important for development and progression of breast cancer." (PMID 24626992, 2014).